RB1 (RB transcriptional corepressor 1)
Diseases named in the same sentence as RB1 in open-access papers (continued):
Sharing a sentence is not in itself a finding about the gene and the disease.
phyllodes tumor (6 papers, 2016 to 2025). A benign, borderline, or malignant fibroepithelial neoplasm arising from the breast and rarely the prostate gland. "The loss of 13q in phyllodes tumors indicates a potential role for the RB1 gene in phyllodes tumor oncogenesis or progression." (PMID 39996866, 2025).
renal cell carcinoma (6 papers, 2014 to 2025).
soft tissue tumors (6 papers, 1989 to 2023). "Deletion of Retinoblastoma 1 (RB1), a well-known tumor suppressor gene, has been implicated in the tumorigenesis of a particular group of soft tissue neoplasms." (PMID 33802620, 2021). "It's role in the diagnosis of SAF and other “RB1‐deleted soft tissue tumours” has been more recently described." (PMID 36092267, 2022). "As adipocytic tumors are frequently encountered in daily practice, accounting for about half of all soft tissue neoplasms, RB1-deleted mesenchymal tumors are often considered in the differential diagnosis." (PMID 33802620, 2021). "RB1-deleted soft tissue tumors are most-commonly seen in the older adult population, usually in patients older than 50 years of age." (PMID 33802620, 2021). "This contemporary review on ‘the rapidly expanding group of RB1-deleted soft tissue tumors’ highlights the clinicopathologic features of this heterogeneous group of mesenchymal neoplasms." (PMID 33802620, 2021). "This group of so-called “RB1-deleted soft tissue tumors” has been rapidly expanding in recent years, currently consisting of spindle cell/pleomorphic lipoma, atypical spindle cell/pleomorphic lipomatous tumor, pleomorphic liposarcoma, myofibroblastoma, cellular angiofibroma, and acral fibromyxoma." (PMID 33802620, 2021). "Information concerning the anatomic location of an RB1-deleted soft tissue tumor may be crucial in making the correct diagnosis, especially as some of these tumors occur almost exclusively in particular anatomic regions." (PMID 33802620, 2021). "Alterations in RB1 are thoroughly investigated in soft tissue tumors." (PMID 19077296, 2008).
thyroid tumor (6 papers, 2013 to 2023). A benign or malignant neoplasm affecting the thyroid gland. "Moreover, evidences of NE differentiation in tumors with loss of Rb1 have been reported for other tumor types such as pituitary and thyroid tumors, adrenal glands and prostate." (PMID 27966456, 2017). "Surprisingly, we found that eRapa dramatically extended life span of both female and male Rb1+/− mice, and slowed the appearance and growth of pituitary and decreased the incidence of thyroid tumors commonly observed in these mice." (PMID 23454836, 2013). "Except for the modest decrease in thyroid tumors, this tumor spectrum is similar to Rb1 heterozygotes treated with DR compared to those fed ad libitum." (PMID 23454836, 2013).
adenoma (5 papers, 2013 to 2022). A neoplasm arising from the epithelium. "We noticed very few TUNEL positive cells in the adenomas from the LSL-Kras, Rb1+/+ mice at 12 weeks post activation of KrasG12D, suggesting absence of cell death in these lesions." (PMID 23936539, 2013). "Furthermore, we also detected similar senescence staining in the AAH lesions and in adenomas from LSL-Kras, Rb1+/+ and LSL-Kras, Rb1∆L/∆L mice." (PMID 23936539, 2013).
chronic lymphocytic leukemia (5 papers, 2011 to 2023). "Deletions or translocations involving chromosomal band 13q14, the locus of the retinoblastoma (RB1) gene, are observed in a variety of hematological malignancies including myelofibrosis (MF), MDS, AML, chronic myelogenous leukemia (CML) and chronic lymphocytic leukemia (CLL)." (PMID 21851601, 2011).
COVID-19 (5 papers, 2022 to 2024). A disease caused by infection with severe acute respiratory syndrome coronavirus 2. "Based on relationships identified between spike proteins and COVID-19 symptoms during analysis of pre-vaccinated samples, plasma for all samples were only analyzed for SARS-CoV-2 spike proteins NCP, NTD, RB1, RBD2, and ST4." (PMID 36083883, 2022).
dysplasia (5 papers, 2008 to 2021). A usually neoplastic transformation of the cell, associated with altered architectural tissue patterns.
ischemia (5 papers, 2013 to 2023). A hypoperfusion of the BLOOD through an organ or tissue caused by a PATHOLOGIC CONSTRICTION or obstruction of its BLOOD VESSELS, or an absence of BLOOD CIRCULATION. "The objectives of this study were to investigate the protective effects of RB1 and its underlying mechanism on renal injury induced by intestinal ischemia-reperfusion (IIR) in mice." (PMID 24324637, 2013). "In GCI (2VO) rats, Rb1 pretreatment protected against hippocampal CA1 neuronal death at the acute stage of ischemia." (PMID 31068769, 2019). "It has been known that Rb1 protects hippocampal neurons against either ischemia or glutamate-induced neurodegeneration." (PMID 24223941, 2013). "It was shown that GST and Rb1 increased the numbers of neuronal precursors and promoted the proliferation of endogenous neural stem cells, thus promoting the behavior recovery post-ischemia." (PMID 31068769, 2019).
leiomyoma (5 papers, 2012 to 2023). A well-circumscribed benign smooth muscle neoplasm characterized by the presence of spindle cells with cigar-shaped nuclei, interlacing fascicles, and a whorled pattern. "The diagnosis of mitotically active leiomyoma was associated with immunopositivity for Rb1, while that of leiomyoma with bizarre nuclei was associated with immunonegativity for Rb1 (p = 0.019)." (PMID 37373854, 2023).
myocardial ischemia (5 papers, 2014 to 2021). A disorder of cardiac function caused by insufficient blood flow to the muscle tissue of the heart. "PNS and its major activity components Rg1, Rb1 and R1 suppressed tumor growth and simultaneously attenuated myocardial ischemia." (PMID 24903055, 2014). "To address this, we established the model of lewis lung carcinoma coupled with myocardial ischemia in mouse, and investigated the effects of PNS and its major activity components Rg1, Rb1 or R1 on the tumor growth and myocardial ischemia in this complex model." (PMID 24903055, 2014). "More importantly, Rb1 shows certain pharmacological effects in maintaining blood circulation, improving myocardial ischemia, anti-arrhythmia, anti-shock, anti-diabetic, improving intelligence, anti-aging, anti-oxidation, anti-cell proliferation, and anti-tumor." (PMID 30823412, 2019). "Rb1 attenuates myocardial ischemia/reperfusion injury and reduces infarct size, cardiomyocyte apoptosis, and caspase-3 activity, partly by inhibiting oxidative stress and apoptosis, enhancing eNOS expression, and increasing NO concentrations, as well as activating the PI3K/Akt pathway." (PMID 30823412, 2019). "Rb1 is a major active component of Panax ginseng, whose protective action against a few CVDs, including abdominal aortic aneurysm, hypertension-induced carotid arterial remodeling, myocardial ischemia/reperfusion injury, and hypertrophy, has been recently proved by in vivo and in vitro studies." (PMID 34712140, 2021). "Furthermore, whether PNS, Rg1, Rb1 or R1 could simultaneously exert proangiogenic and antiangiogenic effect when myocardial ischemia is complexed with tumor is unknown." (PMID 24903055, 2014). "Treatment with QSYQ, AS-IV, and Rb1 but not Rg1, R1, or DLA significantly prevented ATP/ADP from decreasing by cardiac ischemia." (PMID 29755361, 2018). "ATP 5D protein expression decreased significantly after cardiac ischemia, in comparison with S+Sham group, which was prevented by treatment with QSYQ, AS-IV, and Rb1, but not Rg1, R1 or DLA." (PMID 29755361, 2018).
neurofibroma (5 papers, 2013 to 2024). An intraneural or extraneural neoplasm arising from nerve tissues and neural sheaths.
Parkinson disease (5 papers, 2012 to 2024). A progressive degenerative disorder of the central nervous system characterized by loss of dopamine producing neurons in the substantia nigra and the presence of Lewy bodies in the substantia nigra and locus coeruleus. "So far none of these complexes was associated to Parkinson disease; however aberrant activation of the RB1-E2F pathway was observed to mediate neuronal cell death and its inhibition was proposed as a possible strategy for neuroprotection." (PMID 22279562, 2012).
penile cancer (5 papers, 2013 to 2024). A primary or metastatic malignant neoplasm that affects the penis.
rhabdoid tumor (5 papers, 2013 to 2024). An aggressive malignant embryonal neoplasm usually occurring during childhood. "Further supporting this interplay, loss of RB1 is a mechanism of resistance to EZH2 inhibition in rhabdoid sarcoma; upon RB1 silencing, tazemetostat no longer downregulated CCNA2." (PMID 38405800, 2024).
chronic kidney disease (4 papers, 2021 to 2026). Impairment of the renal function secondary to chronic kidney damage persisting for three or more months. "The RB1 gene located at 13q14.2 has been associated with diabetic cardiomyopathy, chronic kidney disease, and proteinuria, all phenotypes that are associated with kidney function and DKD." (PMID 36949158, 2023). "The therapeutic implications of Rb1 may extend beyond AKI, as compelling evidence links incomplete recovery from AKI to progressive chronic kidney disease (CKD) via persistent tubular injury, oxidative stress and fibroblast activation." (PMID 41508002, 2026).
cutaneous melanoma (4 papers, 2019 to 2020). A primary melanoma arising from atypical melanocytes in the skin.
depression (4 papers, 2019 to 2026). "TLR4 and RB1 were identified as core genes, showing elevated expression and strong diagnostic potential in depression." (PMID 42253512, 2026). "Unfortunately, very little is known about Rb1's antidepressant-like effect on behavioral impairments caused by CSDS, or on the exact neuronal processes underlying, or about Rb1's significance to the neuroprotective effect of slowing the inflammatory process in depression." (PMID 35634375, 2022). "The study explored the pharmacological properties of Rb1 and revealed that Rb1 could be an important candidate molecule in the prevention and treatment of disorders associated with stress, including depression, exerting considerable effects and relatively few adverse effects." (PMID 34658847, 2021). "In brief, the current study revealed that Rb1 prevents depression-like symptoms in socially defeated mice, which seems to be facilitated via activation of the hippocampal BDNF–TrkB signaling pathway." (PMID 34658847, 2021). "In the current study, it was revealed that Rb1 exerts an antidepressant-like effect in a CSDS-induced depression model." (PMID 34658847, 2021). "In conclusion, our results indicated that Rb1 exerts promising antidepressant-like effects in mice with CSDS-induced depression, and its effects were facilitated by enhancing the BDNF signaling cascade and upregulation of hippocampal neurogenesis." (PMID 34658847, 2021). "Our results asserted that the Rb1 is a novel therapeutic candidate for treating depression." (PMID 35634375, 2022). "Moreover, this study highlights Rb1 as a candidate novel therapeutic agent for the prevention and treatment of depression." (PMID 35634375, 2022). "However, several studies have demonstrated that Rb1 has therapeutic potential against depression-like conditions and that it exerts an antidepressant-like effect against behavioral abnormalities caused by CSDS; however, its underlying mechanism is not fully understood." (PMID 34658847, 2021). "In the current study, it was revealed that Rb1 treatment enhanced the phosphorylation of AKT and ERK1/2, two downstream regulators of BDNF, in the hippocampus and alleviated depression symptoms in CSDS mice." (PMID 34658847, 2021). "Collectively, our research indicates that Rb1 exerts antidepressant-like effects in a mouse model of CUMS-induced depression by promoting BDNF signaling, thus providing new insights into the pharmacological effects of Rb1 in the treatment of depression." (PMID 31572200, 2019). "In addition to depression, BDNF signaling is also involved in other neurological disorders such as anxiety and epilepsy, suggesting that Rb1 may also be beneficial for treating these diseases; however, this requires further experimental evidence." (PMID 31572200, 2019).
endometrioid ovarian carcinoma (4 papers, 2022 to 2025). "RB1 loss was associated with longer OS in HGSC but with poorer prognosis in endometrioid ovarian carcinoma." (PMID 38837893, 2024). "RB1 loss was most frequent in HGSC (16.4%), followed by endometrioid ovarian carcinoma (ENOC; 4.1%, χ2P < 0.0001)." (PMID 38837893, 2024).
hepatitis B (4 papers, 2007 to 2025).
hereditary cancer (4 papers, 2005 to 2025). Malignant neoplasms occurring in families at a rate greater than that expected by chance and caused by germline mutations in a specific gene. "The NovoFocus CR clinical NGS panel was used to evaluate germline alterations in 106 genes associated with hereditary cancers including RB1." (PMID 36173648, 2022). "The most significant finding is the occurrence of multiple, distinct hematologic secondary malignancies in a patient with no germline RB1 mutation or other known hereditary cancer predisposition." (PMID 41307228, 2025).
Lynch syndrome (4 papers, 2018 to 2025). An autosomal dominant hereditary neoplastic syndrome characterized by the development of colorectal carcinoma and a high risk of developing endometrial carcinoma, gastric carcinoma, ovarian carcinoma, renal pelvis carcinoma, and small intestinal carcinoma. "Whole‐genome mRNA expression profiles of 41 tumors and immunohistochemical stainings against FGFR3, KRT5, CCNB1, RB1, and CDKN2A (p16) of 37 tumors from patients with Lynch syndrome were generated." (PMID 29791078, 2018).
malignant glioma (4 papers, 2003 to 2024). A grade III or grade IV glioma arising from the central nervous system. "With regard to malignant glial tumours, we found significant RB1 methylation rates in the group of GB (21% of samples)." (PMID 12556968, 2003).
memory impairment (4 papers, 2019 to 2024). "Rb1 reversed memory impairment induced by aluminum (Al)—exposure, probably through preventing tau hyperphosphorylation by regulating p-GSK3 and PP2A level in the cortex and hippocampus." (PMID 32587516, 2020). "Our study indicates that Rb1 has potential as a therapeutic agent for PD patients with memory impairment." (PMID 30958793, 2019). "The non-spatial memory improvement effect of Rg1 was reported in previous researches, which found Rg1 improved scopolamine (SCOP) induced memory impairment in a step-through test and both Rg1 and Rb1 can improve the impaired memory performance induced by SCOP in step-down passive avoidance test." (PMID 32587516, 2020). "Aging mice had spatial learning and memory impairment, and the escape latency of mice after Rb1 and Re intervention was significantly reduced compared with that of the aging model group, which indicated that Rb1 or Re intervention alone could effectively improve the cognition of the aging model." (PMID 39346650, 2024). "The findings of these two behavioral tests provided evidence for Rb1 and Rg1-mediated amelioration of HLS-induced learning and memory impairment." (PMID 37168997, 2023).
mesenchymal neoplasm (4 papers, 2020 to 2022). "Mesenchymal tumors with RB1 loss represent a heterogeneous family of neoplasms with different morphologic and clinical features, all showing a high incidence of RB1 deletions." (PMID 33802620, 2021). "RB1 loss has also been reported in other mesenchymal neoplasms, such as well-differentiated liposarcomas, myxofibrosarcomas, and undifferentiated pleomorphic sarcomas." (PMID 33802620, 2021). "In recent decades, the role of RB1 loss and the inactivation or dysregulation of RBp function by RB-associated proteins have been implicated in many cancer types, e.g., melanomas, osteosarcomas, small-cell lung cancer, and several mesenchymal tumors." (PMID 33802620, 2021). "Cellular angiofibroma is a rare benign mesenchymal neoplasm most commonly occurring in the vulvovaginal region in women and the inguinoscrotal region in men with specific genetic deletion involved in the RB1 gene in chromosome 13q14 region." (PMID 31936598, 2020).
metastatic melanoma (4 papers, 2010 to 2021). A melanoma that has spread from its primary site to another anatomic site. "The mRNA expression of several genes involved in cell cycle control and/or proliferation, including the Cyclins B3, E1, G1 and G2; PCNA and RB1 were also decreased in metastatic melanoma." (PMID 21615965, 2011).
myofibroblastoma (4 papers, 2015 to 2022). A benign, well circumscribed soft tissue neoplasm characterized by the presence of spindle shaped myofibroblasts and mast cells in a collagenous stroma. "The main differential diagnosis includes other benign tumors with RB1 deletion such as myofibroblastoma and SCL." (PMID 33802620, 2021).